GPER1 (G protein-coupled estrogen receptor 1)
Diseases named in the same sentence as GPER1 in open-access papers (continued):
Sharing a sentence is not in itself a finding about the gene and the disease.
cancer (continued). "Earlier, we showed that GPER1 expression affected the OS from 11 cancers." (PMID 37921845, 2023). "Although an increasing number of studies have focused on the role of GPER1 in different types of cancers, it remains controversial whether GPER1 plays a pro- or anti-cancer role in tumours." (PMID 37921845, 2023). "GPER1 is expressed by many hormone-sensitive tumor entities and rapidly activates signaling cascades mediated by estrogen, making it a potential target for carcinoma treatment." (PMID 37762008, 2023). "GPER1 has even been proposed to be a poor prognostic marker in different kinds of cancer." (PMID 36231664, 2022). "GPER1 is likely involved in the proliferation, migration, and invasion of cancer cells." (PMID 36060947, 2022). "In the context of cancer, GPER1 may play important roles in regulating cellular proliferation, increases in tumor size, distant metastasis, and tumor recurrence." (PMID 36231664, 2022). "However, there is contradictory evidence indicating that GPER1 act as either a tumor promoter or a tumor suppressor in different cancer contexts." (PMID 33425895, 2020). "(The role of GPER1 in cancer is the object of a specific review, in this special issue)." (PMID 33133022, 2020). "However, GPER1 has contradictory roles as either a tumor-suppressor or a tumor-promoter in, depending on the specific cancer context." (PMID 33425895, 2020). "Few studies have investigated whether GPER-1 regulates cell proliferation in mouse-derived neural stem/progenitor or prostate stromal cells and most related studies have focused on cancer cells." (PMID 32899453, 2020). "Growing evidence has shown that activation of GPER1 in several cancer cells, as well as in CAFs, may induce the expression of diverse genes, like c-fos, cyclin D1 and CTGF, involved in important biological effects, including cell proliferation and migration." (PMID 33374170, 2020). "GPER1 has been reported to be able to couple to a wide range of signalling pathways both when expressed heterologously in clonal cell lines or homologously in a range of cancer cell lines and native tissues." (PMID 26998610, 2016). "However, preclinical studies also found that GPER-1 activation of its special agonist G-1 inhibits cancer cell proliferation." (PMID 27314054, 2016). "This review aims to summarize the characteristics and complex functions of GPER-1 in cancers." (PMID 27314054, 2016). "The promotion roles of GPER-1 in cancer cells proliferation and migration may be correlated with the autolysis of calpain 1, cleavage of cyclin E, or the expression of target gene." (PMID 27314054, 2016). "Although increasing studied are focused on the roles of GPER-1 in different types of cancers, the functions of GPER-1 in cancers remain unclear yet." (PMID 27314054, 2016). "Knowing the GPER1 interactome might help understand its functions, resolve its signal transduction pathways, and facilitate the development of effective therapies, for example, in the context of cancer." (PMID 37947649, 2023). "Furthermore, GPER1 is considered a potential therapeutic target for cancer treatment." (PMID 37921845, 2023). "Depending on the cancer type, GPER1 activation might promote or inhibit carcinogenesis." (PMID 37759449, 2023). "In all samples from patients with tumour, GPER1 gene mutations decreased OS, DFS, DSS and PFS, suggesting that GPER1 gene alterations play an important role in cancer progression and that the associated changes in GPER1 expression levels could provide prognostic value for patients with tumour." (PMID 37921845, 2023). "Evidence has suggested that GPER1 may be a prognostic predictive marker for these cancers." (PMID 37921845, 2023). "GPER1 signaling appears to have an important role in regulation of inflammatory response in various systems, including the vasculature, adipose tissue, gastrointestinal tract, and central nervous system, as well as in pathologies such as cardiovascular disease, nephrotoxicity, and cancer." (PMID 35327604, 2022).
cancer (continued). "However, there are few reports on the molecular effects of GPER1 in this type of cancer." (PMID 36231664, 2022). "The recognition and functional characterization of novel compounds that act as ligands of GPER1 represents a valuable means of further dissecting this receptor’s pharmacology, and better understanding how its functions are elicited in different types of cancer." (PMID 36231664, 2022). "Therefore, evaluating the activation of GPER1 in this type of cancer is also important." (PMID 36231664, 2022). "Furthermore, GPER1 expression was found to be higher in HCC tissue than in cancer-adjacent tissue." (PMID 33425895, 2020). "In addition to the mentioned ongoing phase 2 study examining the effect of E2-triggered ERβ activation in TNBC, further in vivo studies and clinical trials are necessary to elucidate the eligibility of ERRs or GPER-1 as targets for endocrine treatment of this cancer entity." (PMID 33114740, 2020). "In this context, it has been reported an intracellular localization of GPER1, in particular bound to endoplasmic reticulum and co-localized in the Golgi apparatus and nuclear membrane in endothelial, vascular smooth muscle cells and pancreatic islet cells as well as in diverse cancer cell types." (PMID 33374170, 2020). "However, CCL18 may also reduce cancer cell migration by activating GPER1/GPR30, where this chemokine interferes with the action of CXCR4 on pre-B acute lymphotic leukemia cells." (PMID 33114763, 2020). "These give a hint that GPER-1 may be a novel therapeutic target for the estrogen-related cancers." (PMID 27314054, 2016). "In ER-positive breast cancer, estrogen-mediated MORC2 phosphorylation via the GPER1 pathway inhibits chaperone-mediated autophagy, leading to increased MORC2 protein expression and promoting cancer cell proliferation and metastasis." (PMID 40760337, 2025). "Clinical trials have recently been conducted on a GPER1 agonist called LNS8801, specifically for its use in combination therapies with ICIs in cancer treatment." (PMID 39582864, 2024). "These 61 FT sEV proteins play an important role in biological processes related to cancer biology and immune response, including RAGE receptor binding, GPER1 signaling, and neutrophil degranulation." (PMID 37106610, 2023). "Thus, this study aimed to perform molecular simulation studies of 17β-AEs with GPER1, and corroborate their proliferative effects in cancer cell lines to assess whether these compounds represent potential therapeutic options for HRT in women going through menopause." (PMID 36231664, 2022). "In this review article, we discuss the role of ERβ and GPER-1 as mediators of E2 action in TNBC as well as the function of ERRs as activators and modulators of estrogen signaling in this cancer entity." (PMID 33114740, 2020). "Estrogen-related receptors (ERRs) and GPER-1 are receptors known to activate or modulate estrogen signaling in TNBC and thus are additional potential targets for therapy of this cancer entity." (PMID 33114740, 2020). "Consistent with the earlier results, the existence of the AMF/GPER-1/PI3K axis in EC cells, which mediates cancer cell growth to assist EC progression, was confirmed." (PMID 30836961, 2019). "Furthermore, pharmacological inhibition of GPER-1 or inhibition of its expression by interfering RNA (siRNA) techniques reverses EMT and reduces the invasiveness of cancer cells." (PMID 39936103, 2025). "We then analyzed by RT–PCR the mRNA level of EGFR and of a small number of proteins involved in its activation and/or having prognostic value in cancer diseases: MMP-2 and -9; uPA; G Protein Coupled Receptor 1 (GPER1); Estrogen Related Receptor alpha (ERR-alpha); SRC; LDH-A and -B; HBEGF." (PMID 39329717, 2024). "Despite the increasing interest in the role of GPER1 in cancer development, no pan-cancer analysis has been available for GPER1." (PMID 37921845, 2023).
cancer (continued). "Evaluation of the H-scores for GPER1 in 148 tissue specimens using the Vectra Multispectral Imaging System demonstrated that there were no obvious differences between the overall cancer tissues and normal control tissues (p > 0.05)." (PMID 37762356, 2023). "Despite comprehensive pan-cancer analyses exploring ERs as prognostic markers and therapeutic targets across different cancers, a comprehensive pan-cancer analysis of GPER1 is lacking to date." (PMID 37921845, 2023). "The investigation extended to GPER1’s intricate relationship with the immune microenvironment, revealing both positive and negative correlations with immune components in different cancers." (PMID 37921845, 2023). "While the role that GPER1 has in the modulation of E2-responsive tissues and cancers is well documented, the molecular mechanisms that regulate GPER1 expression are currently not well defined." (PMID 31242463, 2019). "Recently the G-protein-coupled receptor 30 was claimed to be a new membrane-bound G-protein-coupled estrogen receptor-1 (GPER-1) involved in the rapid nongenomic effects of estrogen in normal and cancer tissue." (PMID 23849542, 2013). "Since n-3 PUFAs enhance/promote GPER1-cAMP-PKA signaling pathway response to E2, which mediate the inhibitory effect of E2 on ER+ BCa cell, it is possible to employ n-3 PUFAs to strengthen the anti-cancer effect of Tamoxifen." (PMID 23285198, 2012). "The negative or positive correlation between GPER1 and both immunosuppressive and immunostimulatory factors may explain why no conclusive conclusion can be reached on whether GPER1 is cancer-promoting or -suppressing despite the numerous studies." (PMID 37921845, 2023). "In addition, BBR could inhibit MDA-MB-231 cells as an agonist of GPER1 by inhibiting the nuclear translocation of RELA, which indicated NF-κB inhibition and anti-cancer effects." (PMID 34768896, 2021). "Agonists of GPER1, such as 1-[4-(6-bromobenzo dioxol-5yl)-3a,4,5,9b-tetrahydro-3H-cyclopenta[c]quinolin-8-yl]-ethanone (G-1) have been tested as an anticancer by suppressing cancer cell proliferation." (PMID 32872134, 2020). "However, comprehensive pan-cancer analysis of GPER1 remains lacking." (PMID 37921845, 2023). "G-protein coupled estrogen receptor 1 (GPER-1) is a transmembrane receptor belonging to the family of G-protein-coupled receptors (GPCRs); it acts independently of estrogen receptors ERα and ERβ and is involved in rapid nongenomic effects of estrogen in normal and cancer tissue." (PMID 33114740, 2020). "Conversely, G protein-coupled estrogen receptor 1 (GPER) and integrin αvβ3 have been shown to play oles in non-genomic actions that contribute to estrogen-induced cancer growth." (PMID 41294885, 2025). "Recently, ERα‐36 has been shown to physically interact with GPER1 in SKBR3 (ERα‐66 negative) and MCF‐7 breast (ERα‐66 positive) cancer cell lines to inhibit proliferation." (PMID 36510342, 2023). "The G-protein coupled receptor (GPCR) sensitive to estrogen (GPER1 or GPR30) appears to mediate many of the rapid, non-genomic actions of estrogen in a wide variety of tissues, including the brain and various cancer cell lines." (PMID 26998610, 2016). "Of interest was the negative correlation between GPER1 and act CD4 in most cancers." (PMID 37921845, 2023).
tumor (269 papers, 2008 to 2026). "Recently, analysis of various databases has shown that DNA methylation of GPER-1 and ERα is associated with survival in tumor patients." (PMID 39936103, 2025). "For example, miRNAs such as miR-9-5p, miR-10b-5p and miR-21-5p are overexpressed and act as oncogenes, promoting GPER-1 expression and suppressing tumor genes such as PTEN and TIMP3, which in turn are associated with increased resistance to treatments." (PMID 39936103, 2025). "Our study found that GPER1 gene mutations were associated with poor prognosis in patients with tumours." (PMID 37921845, 2023). "We also validated in an independent patient cohort, a previously reported observation that the association between GPER1 expression and survival differs depending on gender and tumour stage." (PMID 36293473, 2022). "The research focused on the interactions of GPER1, a molecule recently associated with promoting and maintaining various neoplasms." (PMID 36231664, 2022). "GPER1 activation reduces the recruitment and polarization of the M2 phenotype of tumor-associated macrophages, inhibiting tumor inflammation, and immune suppression." (PMID 33133022, 2020). "SNPs of GPER-1, histone acetylation, and transcription factor recruitment were significantly associated with tumor size and histological grading." (PMID 27314054, 2016). "An association between GPER-1 expression and the tumor variables was evaluated using the x2 test or Fisher’s exact test." (PMID 23849542, 2013). "Interestingly, an overexpression of GPER-1 in ovarian cancer is associated with decreased tumor development." (PMID 39936103, 2025). "Downregulation of GPER1 has been linked to poor prognosis in gastric cancer, and it may function as a tumor suppressor by regulating epithelial–mesenchymal transition in this context." (PMID 39684286, 2024). "For EAC samples, high expression of GPER1 was associated with poor tumor differentiation." (PMID 37762356, 2023). "GPER-1 overexpression could be associated to carcinogenesis and to molecular strategies developed by tumor cells to escape tamoxifen treatment." (PMID 33117280, 2020). "Subsequent in vitro validation confirmed that GPER1 activation mediates the tumour-suppressive effects of estrogen and 27-OHC." (PMID 42047268, 2026). "Collectively, our findings highlight IGFBP-5 as a potential prognostic marker, demonstrate the tumour-inhibitory effect of ERβ silencing, and identify GPER1 as a promising therapeutic target linking estrogen signalling, lipid metabolism, and CRC progression." (PMID 42047268, 2026). "Lower GPER1 expression in macrophages correlates with increased macrophage proliferation and tumor progression, while activation of GPER1 signaling suppresses macrophage proliferation via the MEK/ERK pathway and reduces PD-L1 expression, delaying tumor growth." (PMID 40438106, 2025). "Second, the tumor microenvironment plays a crucial role; the extracellular matrix can modify GPER-1 activity and thus alter tumor responses." (PMID 39936103, 2025). "The ferrocene-linked novel tamoxifen derivatives, T5 and T15, can mitigate the tumor-promoting effects induced by GPER1 through direct viability, decreasing the effect resulting from oxidative stress." (PMID 41011284, 2025). "First, GPER-1 expression and tumor cell type are critical, as GPER-1 shows remarkable versatility in the target signaling pathways it activates, which generates a variable impact depending on the cellular context." (PMID 39936103, 2025). "The correlation between the DNA methylation beta-value and the RNA level of ESR1, ESR2, and GPER1 was analyzed through cBioPortal in 19 tumor types." (PMID 38666956, 2024). "HCT116 ASNS+/+ culture with E2, which increased GPER1, showed a decrease in cell growth, aligning with previous results that show HCT116 ASNS−/− tumors with high GPER1 have decreased tumor size." (PMID 38886847, 2024).
tumor (continued). "GPER1 exhibited an R greater than 0.5 in 6 tumor types, R values ranging from 0.3 to 0.5 in 11 tumor types, and R values less than 0.3 in 2 tumor types." (PMID 38666956, 2024). "GPER1 promotes tumor progression mainly by interacting with carcinogenic signaling pathways, such as the EGFR/ERK1/2 pathway, the PI3K/AKT/mTOR signaling pathway, and the MAPK/ERK signaling pathway." (PMID 38383297, 2024). "Taken together, current data suggest a tumor-promoting role of ERα, but anti-tumoral effects of ERβ and GPER1 in OC." (PMID 39796024, 2024). "In contrast, GPER1 was upregulated in the HCT116 ASNS−/− compared to HCT116 ASNS+/+ tumor xenografts in both male and female mice." (PMID 38886847, 2024). "In a murine model, co-treatment with PD-1 inhibitor and GPER1 agonist G-1 resulted in reduced cell proliferation and tumor volume along with better survival." (PMID 39252786, 2024). "The most inspiring phenomena are the higher expression of ESR2 in the male testis than in the female ovary and endometrium and the consistent reduction of GPER1 RNA in different tumor samples when compared with normal tissues." (PMID 38666956, 2024). "Our previous study found that TCBPA exhibits estrogenic activity and can stimulate the proliferation of MCF-7 estrogen-sensitive tumor cells by activating ERα and GPER1 signaling pathways." (PMID 39058137, 2024). "The association between GPER1 expression and macrophage proliferation was examined in human HCC tumor tissues." (PMID 39582864, 2024). "Statistical analysis revealed that patients with a higher frequency of GPER1+ macrophages exhibited a significantly lower level of macrophage proliferation in tumor tissues." (PMID 39582864, 2024). "Another study set-up observed an inhibition of tumor growth after blockage of GPER1 in an athymic mouse model with a HEC-1A cell line xenograft." (PMID 37345182, 2023). "Taken together, data from these in vitro studies clearly support a tumor-suppressive role of GPER1 in OC." (PMID 37345182, 2023). "To assess the biological impact of GPER1 activation on MM cells, we exploited the selective small molecule G-1, which has been previously demonstrated as a potent agonist of GPER1 in different tumor types." (PMID 37759449, 2023). "We further investigated the relationship between GPER1 and tumour-infiltrating lymphocytes (TILs), immunoinhibitors, immunostimulators, major histocompatibility complex (MHC) molecules, chemokines and chemokine receptors via the TISDB." (PMID 37921845, 2023). "Contrary to the results obtained analyzing the mRNA expression of GPER1, IHC investigations suggest a tumor-promoting role of GPER1 in EC." (PMID 37345182, 2023). "Several studies have shown that activation of GPER1 can promote carcinogenesis, whereas others have shown that its activation can suppress tumours." (PMID 37921845, 2023). "Several substances that are known to exert tumor-suppressive or -promoting effects in OCs act via GPER1." (PMID 37345182, 2023). "For EAC, we found that the positive expression of GPER1 protein increased with poor tumor differentiation (p < 0.05)." (PMID 37762356, 2023). "A small partial positive expression of GPER1 was found in some serous cells and gland duct cells, and obvious positive staining was mainly located on the cell membrane of the tumor tissues." (PMID 37762356, 2023). "On the other hand, the results of an in vitro study employing a single cell line only, OVCAR-5, suggested a tumor-promoting character of GPER1 in OC." (PMID 37345182, 2023). "In a work published by our group, we observed a clear tumor-suppressive action of G-1 in an EC cell line with varying GPER1 expression levels." (PMID 37345182, 2023). "GPER1 expression was observed mainly in the nuclei and sometimes concurrently in the nuclei and cytoplasm of tumor cells, thus positive expression patterns of GPER1 were classified into two classes: nGPER1 and n/cGPER1 expression." (PMID 35664735, 2022).